MGMT (O-6-methylguanine-DNA methyltransferase)
Diseases named in the same sentence as MGMT in open-access papers (continued):
Sharing a sentence is not in itself a finding about the gene and the disease.
temporal lobe tumours (1 paper, 2023). "Factors associated with LMD relapse in this study include younger age, initial temporal lobe tumour location, and unmethylated MGMT promoter status." (PMID 37715122, 2023). "We found that younger patients (< 50 years old), patients with temporal lobe tumours and those lacking MGMT promoter methylation were at increased risk of LMD relapse." (PMID 37715122, 2023).
testicular tumour (1 paper, 2005). "While several testicular tumour suppressor genes have now been identified, only a few, for example RASSF1A, MGMT, have been reported to be silenced in testicular tumours through DNA hypermethylation." (PMID 15685234, 2005).
thyroid tumours (1 paper, 2013). "Little is known about the methylation status of MLH1 and MGMT in thyroid tumours and its association with MSI and mutational status." (PMID 23414134, 2013). "Whether promoter hypermethylation of the MLH1 and MGMT genes is the underlying mechanism associated with presence of BRAF V600E, RAS, IDH1, PIK3CA mutations and/or other genetic alterations found in thyroid tumours is still unknown." (PMID 23414134, 2013). "In a series of 96 thyroid tumours whose mutational profiles of BRAF, IDH1 and NRAS mutations and RET/PTC were previously determined, we investigated MLH1 and MGMT expression and methylation status by qPCR and methylation-specific PCR after bisulphite treatment, respectively." (PMID 23414134, 2013).
tubular adenoma (1 paper, 2006). A usually polypoid neoplasm arising from the glandular epithelium. "Loss of expression of MGMT correlated with KRAS mutation in small tubular adenomas (P < 0.04)." (PMID 16879389, 2006).
vascular tumor (1 paper, 2021). "This is, prognosis of patients with a moderate vascular tumor will be affected by MGMT methylation status, while survival times for the high vascular group do not differ, independently of the MGMT methylation status." (PMID 34771583, 2021).
vulvar tumors (1 paper, 2015). "We report a detailed study of 25 vulva tumors [22 SCC, 2 MM, 1 atypical squamous cell hyperplasia (AH)] analyzed for expression of the high-mobility group AT-hook family member genes HMGA2 and HMGA1, for mutations in the IDH1, IDH2 and TERT genes, and for methylation of the MGMT promoter." (PMID 25823555, 2015).
Werner syndrome (1 paper, 2022). "The hypermethylation promoter activates genes involved in cellular processes such as DNA repair, gene repair 1 (hMLH1), O6-methylguanine-DNA methyltransferase (MGMT), Werner syndrome, as RecQ helicase (WRN), breast 1 WIF-1, and SFRP1." (PMID 36447689, 2022).
tumor (1,754 papers, 1988 to 2026). "The dataset also provides comprehensive genetic information, including IDH mutation-status, 1p19q co-deletion, MGMT promoter methylation, tumor-type, and tumor-grade." (PMID 42020453, 2026). "To integrate SRRS with clinical practice, we developed a nomogram incorporating age, gender, tumor grade, MGMT promoter status (MGMTp), IDH mutation status, and 1p19q codeletion status (PQ)." (PMID 40933894, 2025). "The DNA repair protein O6-methylguanine-DNA methyltransferase (MGMT), linked to tumour resistance against alkylating drugs, is present in GBM and plays a role in conferring resistance to TMZ." (PMID 40558513, 2025). "Pantothenic acid or vitamin B5 has been associated with GBM, and in a recent study, it was one of several metabolites differentially expressed between core and edge tumor specimens in association with MGMT status." (PMID 40362575, 2025). "Previous research shows that peritumoral ADC and texture heterogeneity are linked to tumor infiltration and MGMT methylation status, as the invasive margin reflects both cellular diffusion restriction and vasogenic edema in HGG." (PMID 41584616, 2025). "Conversely, when the MGMT promoter is lowly methylated, gene expression is upregulated, allowing tumor cells to repair DNA damage caused by alkylating agents, leading to resistance to these drugs." (PMID 41394878, 2025). "MGMT repairs this damage, so its promoter methylation or mutation, which silences MGMT, increases tumour sensitivity to TMZ." (PMID 40867329, 2025). "By repairing the DNA damage that TMZ is thought to cause, MGMT acts as a molecular shield inside tumor cells, reducing the therapeutic efficacy of TMZ and causing adverse clinical outcomes." (PMID 40725021, 2025). "Although our work employed an internally validated threshold for positivity as any staining intensity observed in ≥ 36% of tumor cells, previous studies endorsed the use of 0, 5, or 10% positivity cut‐offs for establishing MGMT deficiency." (PMID 39825572, 2025). "Among the five clinical parameters, gender and MGMT status demonstrated stronger positive correlations with most radiomics features, while age, tumor grade, and IDH status exhibited weaker associations." (PMID 40860684, 2025). "MGMT promoter methylation leads to the silencing of the DNA repair enzyme MGMT, making tumor cells unable to repair DNA damage caused by TMZ." (PMID 41201287, 2025). "This review uncovers the nuanced control of MGMT, revealing how its genetic and epigenetic shifts shape tumor behavior, therapeutic response, and risk stratification." (PMID 40895460, 2025). "This dual inhibition causes the accumulation of DNA damage and enhances tumor cell death, particularly in MGMT-deficient settings." (PMID 40895460, 2025). "Proteolysis-targeting chimera (PROTAC) BET degraders (e.g., SPP-ARV-825) achieve selective BRD4 depletion, suppress MGMT, and reprogram tumor-associated macrophages (TAMs) toward pro-inflammatory states." (PMID 41341594, 2025). "Our previous study reported that the loss of MEN1 in pNETs can induce a high level of MGMT expression, which impairs the tumor cell response to TMZ via MEN1 deletion mutation-driven activation of the upstream pathway of MGMT." (PMID 41390817, 2025). "Given the unpredictability in MGMT promoter status, it is useful that this tumor often harbors a high rate of other targetable mutations, which presents an opportunity to study alternative agents." (PMID 40270074, 2025). "Several assays for measuring MGMT deficiency in tumor samples have been developed and clinically evaluated." (PMID 40458731, 2025). "Conversely, cancers such as cervical, esophageal, and thyroid often exhibit MGMT silencing or loss of function, which correlates with tumor progression, CRT resistance, and poorer clinical outcomes." (PMID 40895460, 2025).
tumor (continued). "O6‐methylguanine‐DNA methyltransferase (MGMT) is an important effector protein associated with Temozolomide (TMZ) resistance in various tumours." (PMID 39873425, 2025). "When the MGMT promoter is methylated, the tumor cells are more susceptible to the cytotoxic effects of alkylating agents." (PMID 39944537, 2025). "These mutations are often acquired during tumor evolution and lead to loss-of-function changes in the MGMT protein." (PMID 40895460, 2025). "In stark contrast, the occurrence of MGMT promoter methylation is associated with diminished enzyme expression, which increases tumor susceptibility to temozolomide." (PMID 39286478, 2024). "The MGMT-encoded protein fixes DNA damage caused by alkylating chemicals in a variety of tumor types 61,62." (PMID 38817857, 2024). "MGMT, a DNA repair enzyme, experiences inhibited DNA repair activity when its promoter is methylated, rendering tumor cells more susceptible to the cytotoxic effects of TMZ." (PMID 39716317, 2024). "MGMT methylation in the initial tumor specimen was significantly associated with prolonged survival (p = 0.032)." (PMID 39335591, 2024). "MGMT expression is generally inhibited in tumors by CpG methylation within MGMT promoters, and tumor MGMT hypomethylation is associated with TMZ resistance in GBM patients." (PMID 39195222, 2024). "When the promoter region of MGMT is methylated, the expression of the MGMT enzyme is suppressed, which inhibits DNA repair and makes the tumor cells more susceptible to alkylating chemotherapy drugs such as temozolomide." (PMID 38167551, 2024). "Molecularly, GBM06 was the only tumor with MGMT promoter methylation and a PIK3CA I391M mutation, which does not alter kinase activity, but eventually increases cell proliferation and viability." (PMID 39054369, 2024). "Compared to histological analyses, molecular-level tumor classification historically required days to weeks for complete analysis, which can provide critical tumor subtype information, like MGMT methylation or IDH mutations." (PMID 38958849, 2024). "O6-methylguanine–DNA methyltransferase (MGMT) is a DNA repair enzyme that reverses the DNA damage caused by alkylating agents, resulting in tumor resistance to TMZ and nitrosourea-based systemic therapy." (PMID 38385046, 2024). "The diagnostic performance of signals in evaluating tumor grades, 1p/19q codeletion status and MGMT promoter methylation status." (PMID 39759149, 2024). "We observed that lower concordance in MGMT methylation between tumor and sEV was associated with patients who underwent complete resection." (PMID 38762534, 2024). "A correlation between IDH status, TERT mutations, MGMT methylation, and tumor location characteristics was also studied." (PMID 38893240, 2024). "By reducing the expression of the MGMT gene, which encodes a DNA repair protein, this methylation makes cells more susceptible to the cytotoxic cell death in tumor cells by alkylating agents." (PMID 39767571, 2024). "Smaller tumor size, younger age and methylated MGMT promoters are associated with improved survival." (PMID 39545524, 2024). "Evidence suggested that there is a positive relationship between 1q/19p co-deletion and MGMT methylation status and OS, while tumor grade, age, and risk score were negatively correlated with OS." (PMID 39574472, 2024). "This supports the theory that the tumor's vulnerability to alkylating drugs is correlated with MGMT inactivation caused by aberrant promoter methylation." (PMID 38817857, 2024). "Taken together, these data collectively showed that MGMT deficiency upregulated p21 expression and increased tumor cell apoptosis, and these data further suggested that MEN1 is involved in the β‐Catenin‐MGMT signaling cascade in PanNETs." (PMID 39041891, 2024).
tumor (continued). "Overall, these results suggested that MGMT has a cancer‐promoting function and controls PanNET cell growth and that the loss of MGMT suppressed tumor development." (PMID 39041891, 2024). "Univariable and multivariable logistic regressions were used to estimate odds ratios (ORs) for expressing IDH1 mutation and MGMT promoter methylation, based on each patient’s age, sex, ethnicity, histology, tumour location and extent of resection." (PMID 39767640, 2024). "Molecular markers like isocitrate dehydrogenase (IDH) mutations and O6-methylguanine-DNA methyltransferase (MGMT) promoter methylation status have gained substantial attention for their role in tumor classification, prognosis, and treatment planning." (PMID 39100020, 2024). "We conducted a chi-square test to explore the association between MGMT status and tumor location, which yielded a statistically significant correlation (χ2 = 13.77, p-value = 0.048) between these variables." (PMID 38893240, 2024). "Violin plots indicate that the glycosylation risk score is highly related to these important clinicopathologic characteristics, including age, gender, tumor grade, MGMT methylation, IDH mutation, and 1p19q co-deletion in TCGA and CGGA datasets." (PMID 38293671, 2023). "Influential variables for this phenomenon included frontal tumor location, BA location, WA location, sex, MGMT promoter methylation, and FGFR mutation." (PMID 37074422, 2023). "Apart from SUVmax on TSPO PET, parameters associated with survival were age, MGMT promoter methylation status, and T2-weighted MRI tumor volume." (PMID 37536737, 2023). "The treatment group, WHO Karnofsky performance status, the extent of tumor resection, MGMT status, and the pathological grade of the tumor remained as risk factors for OS independently of other factors." (PMID 36705923, 2023). "Three genes (ARTX, BRAF, and MGMT) contained mutations with a moderate or high impact on protein functions in the original tumor or PDX sample." (PMID 38001935, 2023). "The genetic data included of the IDH1 mutation and MGMT promotor methylation status, while clinical data included age, gender, treatment types, and tumor location." (PMID 36672494, 2023). "The tumor suppressor gene for O6-methylguanine-DNA methyltransferase (MGMT), located on chromosome 10q26.3, encodes a highly evolutionarily conserved enzyme involved in DNA repair." (PMID 36766464, 2023). "A second circulating biomarker associated with poor tumor response to CRT is detection in cfDNA of MGMT promoter hypermethylation." (PMID 36766755, 2023). "We suggest MGMT-methylated tumours represent a less aggressive variant of GBM with a better prognosis." (PMID 37373988, 2023). "We found that PCOLCE expression was significantly correlated with patient age, tumor grade, histology, MGMT methylation levels, 1p19q co-deletion, and IDH mutation (P < 0.001) but not patient gender (P > 0.05)." (PMID 36882457, 2023). "The gene encoding the enzyme, MGMT, is located at 10q26, and methylation of its promoter inhibits gene expression, making tumor cells more vulnerable to TMZ and improving clinical response to the drug." (PMID 37919784, 2023). "MGMT methylation analysis was performed on 65 tumour samples including 47 wtGIST (33 SDH-deficient wtGIST and 11 SDH preserved wtGIST) and 21 tyrosine kinase (TK) mutant GIST." (PMID 36198483, 2023). "Data included tumour location, promoter methylation of O6 methylguanine-DNA methyltransferase (MGMT) and mutation of isocitrate dehydrogenase (IDH), patient age, sex, extent of resection at primary diagnosis and treatment at successive tumour recurrences." (PMID 36730349, 2023). "Loss of MGMT activity is caused by the epigenetic silencing of MGMT, which is achieved by methylating certain CpG islands of its promoter in tumor tissues of different malignancies, including lung tumors." (PMID 37901797, 2023).
tumor (continued). "We investigated the association between age, tumour site, extent of resection, Ki67 index, IDH1 mutation, MGMT promoter methylation and baseline performance status with subsequent tumour relapse." (PMID 37715122, 2023). "Post-CRT CEA levels had the most consistent association with tumor response, while cfDNA integrity index, MGMT promoter methylation, ERCC-1, miRNAs, and miRNA-related SNPs were identified as potential predictive markers." (PMID 36766755, 2023). "MGMT promoter methylation is associated with a loss of MGMT protein expression and activity in the tumor and has been shown to correlate with a better outcome of therapy in several studies." (PMID 37229486, 2023). "The ANOVA (Analysis of Variance) and the t-test were used to analyze the relationship between DACH1 expression and tumor grade, patient age, MGMT methylation status, and IDH mutation status." (PMID 36959804, 2023). "O6-methylguanine-DNA methyltransferase (MGMT) has been linked with alkylating agent resistance and tumor growth suppression." (PMID 37161026, 2023). "The MGMT gene encodes a DNA repair enzyme that removes alkyl adducts from the O6 position of guanine in tumor DNA, which is damaged by alkylating agents such as temozolomide, exerting antitumor effects by impairing DNA replication." (PMID 35397757, 2022). "When its promoter is methylated, the MGMT gene, which is involved in DNA repair, is hindered and the tumor has greater difficulty overcoming the damage caused by chemotherapy such as temozolomide." (PMID 35982952, 2022). "We further analyzed the correlation between the PRM and clinical features (gender, age, BRAF V600E, IDH, KPS, MGMT, and original subtype) and tumor mutation burden (TMB)." (PMID 35783263, 2022). "The association between change in enhancing tumor volume, change in rCBV, MGMT promotor methylation status, and PFS or OS were explored." (PMID 35371980, 2022). "On one hand, it can exert anti-tumor activity by inhibiting abnormal DNA methylation; on the other hand, it can cause abnormal MGMT expression and lead to drug resistance toward alkylating agents in tumor cells." (PMID 37077808, 2022). "Factors significantly associated with longer PFS were higher KPS, frontal versus multifocal tumor location, gross total resection, MGMT hypermethylation, IDH mutation and simultaneous plus sequential TMZ versus no TMZ administration." (PMID 34940951, 2022). "Daily therapy at a dose of 75 mg per square meter for up to seven weeks is safe; at these doses, TMZ depletes the DNA repair enzyme MGMT, resulting in tumor tissue shrinkage, an effect associated with longer survival among glioblastoma patients." (PMID 35203272, 2022). "Factors associated with improved survival were MGMT promoter methylation, adjuvant chemotherapy within 12 weeks, and tumor volume <3 cc." (PMID 35611270, 2022). "The fact that MGMT activity has a major effect on the susceptibility of tumor cells to O6-alkylating medicines has encouraged the search for techniques to reduce MGMT activity in tumor tissue in order to increase the sensitivity of tumor cells to these agents." (PMID 36009577, 2022). "This presupposes, however, that a) the tumor cells are MGMT-deficient, b) the tumor cells proliferate (since the conversion of O6MeG into DSB is strictly replication-dependent) and c) MMR as well as the DDR are not affected by IR." (PMID 35785203, 2022). "Immune characteristics, tumor mutation profile, tumor stemness indices, MGMT methylation, and immunotherapy response biomarkers showed significant differences between high- and low-risk populations." (PMID 35276059, 2022). "A recent study did not establish a significant association between the existence of enhancing tumor margins and the status of MGMT promoter methylation." (PMID 36289752, 2022).